HLA-G (major histocompatibility complex, class I, G)
Diseases named in the same sentence as HLA-G in open-access papers (continued):
Sharing a sentence is not in itself a finding about the gene and the disease.
cancer (continued). "Experimental evidence suggests important contributions of HLA-G and HLA-E to immune escape in many cancers." (PMID 34201079, 2021). "HLA-G expression has been shown in many cancer types, both in primary and metastatic tumors, mainly as soluble HLA-G5, but also associated with EVs." (PMID 34295890, 2021). "HLA-G expression favors the acceptance of allograft organ transplantation, whereas it provides an additional strategy for cancer cells to escape from immune surveillance and clearance." (PMID 34276691, 2021). "Fortunately, ILTs, NKG2A, and HLA-G targeted immunotherapy and signalling pathway blockades are already in development in clinical trials for cancer immunotherapy." (PMID 34938296, 2021). "The aim of this study was to systematically identify the roles of checkpoint HLA-G molecules across various types of cancer." (PMID 34276642, 2021). "HLA-G was detected in cancer cells in 49/148 (33%) effusions, 33/66 (50%) primary tumors, and 59/122 (48%) solid metastases." (PMID 34868081, 2021). "The immune checkpoint molecule human leukocyte antigen-G (HLA-G) as membrane-anchored or soluble molecule represents a compelling factor in the context of both development and progression of cancer." (PMID 35095919, 2021). "It is now widely accepted that HLA-G is an important marker of immune tolerance in cancer cell immune escape and is closely related to the progression and prognosis of cancer patients." (PMID 33767709, 2021). "In this scenario, the interpretation of clinical significance of HLA-G in cancers seems rather premature unless more reliable specific anti-HLA-G mAbs are used." (PMID 34276691, 2021). "Its highly tissue-specific physiological expression profile and immunosuppressive functions have made HLA-G an interesting research topic in recent decades, especially for cancer research." (PMID 34276642, 2021). "HLA-G is a potentially novel immune checkpoint molecule in cancer, but additional evidence is required to provide." (PMID 34276642, 2021). "In this study, we first systematically identified that the expression of HLA-G in various types of cancers." (PMID 34276642, 2021). "Since the first report HLA-G expressed in tumors, the degree or proportion of HLA-G expression in thousands of malignant lesions among over thirty different types of cancers have been explored." (PMID 34276691, 2021). "Taken together, these results indicate that chemotherapeutic agents promote translocation of HLA-G to the cancer cell surface by downregulating DMNT1 expression and TAP-1 promoter demethylation." (PMID 34663641, 2021). "It’s an exciting news released in Cancer Discovery “Gilead Buys into Tizona’s Anti-HLA-G Strategy” that an early clinical trial with human leukocyte antigen-G (HLA-G) inhibitor TTX-080 is being launched for advance solid cancer patients (NCT04485013)." (PMID 34276691, 2021). "In our opinion, the declaration of HLA-G as novel immune checkpoint molecule in cancer is premature." (PMID 34361031, 2021). "Concluding, it remains up to debate what the true impact is of HLA-G expression on clinical patient outcome in these particular carcinoma types due to the scarcity of publications." (PMID 34361031, 2021). "The aim of this review was to uncover to what extent it is justified that HLA-G expression is considered as a target for ICI therapy in carcinomas." (PMID 34361031, 2021). "The majority of included studies used 4H84 as HLA-G-detecting mAb in IHC analysis to quantify the percentage of HLA-G-positive carcinoma samples." (PMID 34361031, 2021). "Not only in used HLA-G-detecting mAbs, quantification methods and stratification variables, but also in conclusions concerning clinical outcome of carcinoma patients." (PMID 34361031, 2021). "The exclusive expression of certain HLA-G isoforms by particular carcinoma types also provides an explanation for why HLA-G expression seems to play different roles in distinct carcinoma types." (PMID 34361031, 2021).
cancer (continued). "In general, a considerable number of questions remain unanswered concerning HLA-G expression in carcinomas, including: what is the most reliable way to quantify HLA-G expression?" (PMID 34361031, 2021). "As long as these questions remain largely unanswered, it is premature to conclude that HLA-G expression is an immune checkpoint molecule in carcinomas." (PMID 34361031, 2021). "The potential role of human leukocyte antigen (HLA)-G as a target for new cancer immunotherapy drugs has increased the interest in the analysis of mechanisms by which HLA-G expression is regulated, and how the expression can be manipulated." (PMID 32560316, 2020). "In this paper, we also investigated the correlation between the survival rates of patients in some cancer types with HLA-G expression." (PMID 32867672, 2020). "Overexpressed HLA-G on cancer cells binds to the inhibitory receptors on effector cells such as CTLs and NKs, leading to the suppression of the cytotoxic activities of these effector cells." (PMID 32222150, 2020). "Upregulation of HLA-G is seen in viral infections, cancer (glioblastoma, melanoma, breast and ovarian cancer, acute leukemia), and other immune-mediated diseases." (PMID 32575403, 2020). "In summary, our study revealed a rather high degree of intratumor heterogeneity of HLA-G expression in cancers, and degree of HLA-G expression is also varied among anti-HLA-G antibodies with different specificities." (PMID 33329527, 2020). "TDEs with HLA-G can require the interaction with target cells that lack the surface expression of HLA-G specific receptors to effect cancer immune escape." (PMID 32580358, 2020). "Patients with HLA-G expression had a worse prognosis.There is a correlation between HLA-G and patient survival and cancer stages." (PMID 33425752, 2020). "There was a highly significant increase in the expression of HLA-G on cancer bladder cases with metastatic prostate infiltration." (PMID 33425752, 2020). "Expression of HLA-G in melanocytes can be induced during malignant transformation mediated by stress and epigenetic mechanisms otherwise employed by the cancer cells to facilitate the oncogenic transformation." (PMID 32560316, 2020). "It has become increasingly evident that the HLA-G molecule is involved in modulating both innate and adaptive immune responses and in promoting immune escape in various types of cancers and infectious diseases." (PMID 32670296, 2020). "HLA-G has a unique expression pattern as it is upregulated in many types of cancers, whereas in normal tissues, its expression is restricted mainly to the extravillous cytotrophoblasts (EVT) of the placenta." (PMID 32019184, 2020). "HLA-G plays a crucial role in protecting the fetus as semi-allogenic transplant from rejection; in cancer as well as in transplant acceptance HLA-G seems to be a key player." (PMID 32575403, 2020). "HLA-G is a well-studied molecule and information regarding its regulatory role in cancer is accumulating." (PMID 32560316, 2020). "The DNA methylation pattern in conjunction with the gene expression pattern obtained from the primary cells, tissue, and cancer cell lines lead us to formulate a model of HLA-G transcriptional control in different type of cells." (PMID 32708387, 2020). "Although HLA-G neo-expression has been proven in numerous tumors, it remains underestimated in most of the cancer lesions." (PMID 32922387, 2020). "Expression of HLA-G following transplantation is associated with a reduced rate of rejection, indicating the importance of HLA-G for the reliability of the human body in exceptional circumstances such as pregnancy, cancer, or transplantation." (PMID 32575403, 2020). "Although the relevance of HLA-G in cancer incidence and development has been proven in numerous tumors, its neo-expression pattern is still difficult to determine." (PMID 32922387, 2020).
cancer (continued). "Knowledge of the association between high‐resolution HLA‐G alleles and 3‐prime untranslated (3′UTR) haplotypes is useful for studies on the role of HLA‐G in transplantation, pregnancy, and cancer." (PMID 32307888, 2020). "HLA-G-bearing EVs are secreted from cytotrophoblast cells, mesenchymal stem cells, and cancer cells." (PMID 32580358, 2020). "It is well established that HLA-G is highly expressed in many cancers and related to immune suppressive microenvironment." (PMID 32123232, 2020). "When it comes to HLA-G surface expression, HLA-G expression is rarely detected on in vitro established cancer cell lines making it challenging to study the molecular function of HLA-G." (PMID 32560316, 2020). "Kaplan-Meier analysis showed the HLA-G deregulation can serve as a prognostic marker for some cancers." (PMID 32867672, 2020). "Herein, we then focused on the interaction of human mast cells expressing KIR2DL4 with HLA-G-positive trophoblasts during pregnancy establishment and with HLA-G-positive cancer cells during cancer progression." (PMID 32023940, 2020). "Since these checkpoint molecules are targets for successful immunotherapy of selected cancers only, it is essential to study the molecular role and function of HLA-G as a possible target for new drugs." (PMID 32560316, 2020). "Previous studies have shown that IFN-γ is able to induce HLA-G expression in a number of cancer cell lines, and that the isoform profile can be regulated by the cytokine environment." (PMID 32560316, 2020). "First, this study is based on a very limited size of patients and types of cancers, the real-world of the heterogeneity of HLA-G expression in more different types of cancers and in larger cohorts of cancer patients remain to be explored." (PMID 33329527, 2020). "The contribution of HLA-G in the pathogenesis of different cancers should therefore be taken into account in future studies." (PMID 33213057, 2020). "Because no genetic alternation that is heavily implicated in the upregulation of HLA-G gene, such as copy number gain or translocation, is detected in cancer genome, elevated HLA-G promoter activity is thought to be crucial for its expression in tumors." (PMID 33425752, 2020). "These strategies should be an important focus of future studies that aim to develop immune checkpoint inhibitors to block the interaction between HLA-G and its receptors for the treatment of cancer." (PMID 33213057, 2020). "We investigated the expression of HLA-G and PD-L1 with the different stages of cancer cell division along with their role in the interaction of immune cells in vitro." (PMID 32961872, 2020). "Combined, our data highlight that analyses of HLA-G functionality should be extended to discrete structures reinforcing its complexity in the periphery of cancer patients." (PMID 32973812, 2020). "A large body of studies have evidenced that higher degree of HLA-G expression in cancers is related to disease progression and worse clinical outcome." (PMID 33329527, 2020). "In tumors, HLA-Gs transfer quickly from APCs or cancer cells to T and NK cells, and convert these cells into temporarily suppressor HLA-G+ cells." (PMID 30899759, 2019). "Neo-ectopic expression of HLA-G as a vesicular form can be considered as a critical factor for cancer progression." (PMID 31382533, 2019). "HLA‐G expression in cancer cells can directly mediate immune tolerance by interacting with inhibitory receptors such as ILT2 and ILT4 expressed on immune cells." (PMID 31489189, 2019). "In order to measure HLA-G molecules in autoimmune and cancer patients, HLA-G specific ELISAs were developed using monoclonal antibodies against HLA-G." (PMID 31779209, 2019). "The implication of HLA-G in cancer development has been reported in different cancers and populations." (PMID 31759373, 2019). "Expression of the tolerogenic HLA-G molecule is considered to confer cancer cells to induce survival environment by suppressing the activation of immune cells." (PMID 31779209, 2019).
cancer (continued). "HPV and HLA-G have been reported to modulate immune responses by altering cytokine profiles and manipulating the signaling pathways in cancer." (PMID 30859089, 2019). "The potential advantage of soluble HLA-G as a biomarker has already been proposed in cancer, chronic viral infections and in vitro fertilization." (PMID 31235762, 2019). "In summary, Qa-2 has been found to have a different role in cancer with respect to its putative human homolog HLA-G." (PMID 30574154, 2018). "Intratumor heterogeneity is very common in cancers; however, information on intratumor HLA-G heterogeneity is rather limited." (PMID 30319626, 2018). "Many efforts have been made by multiple laboratories worldwide to assess the expression and clinical significance of HLA-G expression in cancers." (PMID 30319626, 2018). "It is still unclear why the expression patterns of HLA-G in HLA-G-negative and HLA-G-positive cancer cells are so different upon hypoxic stress." (PMID 30061885, 2018). "There are many reports on the possible role of HLA-G in cancer immunosuppression, but very little on the role of iron." (PMID 30400822, 2018). "HLA-G has been found to be an independent predictive factor for poor outcome at least in some cancers." (PMID 29464090, 2018). "Different clinical significance of HLA-G expression in cancers detected with mAb 4H84 and mAb 5A6G7 was also reported in previous studies." (PMID 30234020, 2018). "Particularly relevant to understand the different roles of HLA-G and Qa-2 in cancer is to identify the specific receptors for Qa-2 in different immune cells, either inhibitory or stimulatory, and the regulatory signals triggered upon its binding." (PMID 30574154, 2018). "The type and localization of HLA-G expressed in the EwS microenvironment is critical to determine its significance in this cancer and to develop HLA-G blocking strategies." (PMID 29464090, 2018). "We hope this study will stimulate researchers to investigate the role of HLA-G and iron as therapeutic targets of the cancer microenvironment." (PMID 30400822, 2018). "Since Paul's first report, HLA-G expression has been analyzed and evaluated worldwide in thousands of malignant samples of various types of cancers." (PMID 30319626, 2018). "Whereas, both HLA-G and Qa-2 are involved in immune tolerance in pregnancy, the current evidence suggests that they play opposite roles in cancer." (PMID 30574154, 2018). "Up till now, several reports showed that hypoxia upregulates HLA-G expression in human cancer cells, but very few studies have been published on the effects of hypoxia on other MHC-I molecules in tumors." (PMID 30061885, 2018). "This highly tissue-specific expression profile and its immune-suppressive function makes HLA-G an interesting target, especially for cancer research." (PMID 29587858, 2018). "It is worth to mention that soluble HLA-G levels are significantly higher in benign lesions than in malignant tumors and can be used as a diagnosis tool to distinguish premalignant from malignant stages." (PMID 30574154, 2018). "HLA-G expression is very restricted in adult normal tissues, but is frequently induced in numerous malignant tumors, such as glioblastoma, melanoma, and cervical tumors, contributing to their immune escape." (PMID 30061885, 2018). "Apart from this specific function, HLA-G shares with classical HLA class Ia molecules the ability to present antigens, suggesting a role for HLA-G on the immune defense against infection and anti-cancer response." (PMID 30574154, 2018). "The cancer promoting function of HLA-G, such as rendering comprehensive suppressive roles to various types of immune component cells and enhancing the proliferation and accumulation of immune regulatory cells have been extensively investigated." (PMID 30234020, 2018). "The immune checkpoint HLA-G prevents maternal rejection of the fetus and contributes in cancer invasion and acceptance of allografts." (PMID 28045999, 2017).
cancer (continued). "Expression of HLA-G on the surface of cancer cells is determined by a plethora of environmental factors, including hypoxia, stress, some hormones, cytokines and viruses." (PMID 28376925, 2017). "In conclusion, in this review, we highlighted the complex interplay between hypoxia and HIF-1 in control of HLA-G induction in human cancer cells." (PMID 28781970, 2017). "Differential expression of HLA-G has been observed among cancer types and tumors from individuals with the same type of cancer; however, its clinical significance is rather limited." (PMID 29296176, 2017). "Otherwise, the use of DNA methylation inhibitors such as 5-aza-2′deoxycytidine (5-aza-dC; decitabine) has been proposed in cancer therapy and was demonstrated to induce HLA-G expression in vitro." (PMID 27577073, 2016). "Based on the functionality of receptors and their expression profile, membrane-expressed and soluble forms of HLA-G molecules are involved in immune regulation in pregnancy, inflammation, and cancer." (PMID 27199995, 2016). "It is important to understand how the trophoblast cells and HLA-G-expressing cancer cells are partly similar to each other." (PMID 27999823, 2016). "HLA-G expression has, besides in cancer, also been found in other pathological situations such as transplantation and viral infections." (PMID 27999823, 2016). "In contrast, in pathological conditions, like infections and cancer, in which a vigorous and maintained immune response is desirable, the expression of HLA-G is detrimental." (PMID 27800497, 2016). "We aimed to elucidate the mechanisms of HLA-G activation under conditions combining hypoxia-mimicking treatment and 5-aza-2′deoxycytidine, a DNA demethylating agent used in anti-cancer therapy which also induces HLA-G." (PMID 27577073, 2016). "The first in vivo existence of HLA-G-bearing EVs was reported for ascites and pleural exudates derived from cancer patients." (PMID 27199995, 2016). "In cancer, it has deleterious escape-effects and the expression of HLA-G by the tumour cells seems to accelerate relapse." (PMID 27800497, 2016). "Studies have shown that HLA-G is expressed in a variety of cancers, such as hepatocellular carcinoma, gastric cancer, and breast cancer, and is correlated with a poor survival." (PMID 27999823, 2016). "The role of HLA-G (through the interaction with LILRB1) in the control of antitumor immune response has also been confirmed both in cancer patients and in murine models of human tumors." (PMID 27652273, 2016). "Previous studies reinforced HLA-G expression was strongly related to poor prognosis in different types of cancers." (PMID 25689063, 2015). "Our findings revealed that we have potentiated the antitumor activity of NK cells by extending their killing efficacy to HLA-G+ resistant cancer targets." (PMID 26460949, 2015). "Altogether, these observations emphasize the need to circumvent HLA-G inhibition in cancer immunotherapies." (PMID 26460949, 2015). "Preclinical models have shown that the expression of HLA-G on cancer cells renders them more metastatic and significantly decreases survival in mice." (PMID 26460949, 2015). "The potential clinical relevance of HLA-G in cancer as a negative regulator due to its direct or indirect tolerogenic properties to avoid immune cells response, was previously highlighted in several studies." (PMID 26633805, 2015). "HLA-G neo-expression has been detected in several human cancers including melanoma, renal cell carcinoma, breast carcinoma, and large cell carcinoma of the lung." (PMID 25887663, 2015). "Due to the functional impact of the HLA-G protein in cancer immune contexture, and the known correlations of functional-regulatory SNPs in the 3’UTR with the HLA-G protein level, the concept of germline genomic variation is very attractive." (PMID 26633805, 2015). "Human Leukocyte Antigen-G (HLA-G) contributes to cancer cell immune escape from host antitumor responses." (PMID 24741612, 2014).